HLA-B (major histocompatibility complex, class I, B)
Diseases named in the same sentence as HLA-B in open-access papers (continued):
Sharing a sentence is not in itself a finding about the gene and the disease.
ovarian carcinoma (7 papers, 2010 to 2025). A malignant neoplasm originating from the surface ovarian epithelium. "A decreased expression or deletion of HLA-B is associated with high invasiveness and increased malignant potential of ovarian cancer." (PMID 36110943, 2022). "Although we previously reported decreased survival for ovarian cancer patients in association with HLA-B/C downregulation, an association with survival was observed neither at mRNA nor protein level in this study." (PMID 20664601, 2010). "ORFV-PrCoA2/B7 encodes two HLA-B*07-restricted human immunodeficiency virus 1 (HIV-1)- and ovarian cancer (OvCa)-derived peptides and one HLA-A*02-restricted HIV-1 peptide in a minigene format, and served as a control for the CD8+ T cell priming assay." (PMID 34944678, 2021). "Besides, MHC molecules, including HLA-B (cor = 0.365, p = 5.69e-11), HLA-DMA (cor = 0.413, p = 7.02e-14), HLA-DPA1 (cor = 0.475, p = 2.03e-18), HLA-DQA1 (cor = 0.467, p = 8.07e-18), and HLA-E (cor = 0.447, p = 2.6e-16), were significantly correlated with the expression of SUCNR1 in ovarian cancer." (PMID 33062639, 2020).
SARS-CoV infection (7 papers, 2008 to 2023). "Some HLA alleles including HLA-B*4601, HLA-B*0703, HLA-DRB1*1202 HLA-DRB4*01010101, and HLA-Cw*0801 are associated with susceptibility to SARS-CoV infection (Wang S.-F." (PMID 33643932, 2021). "For example, Ng reported that SARS-CoV infection was associated with HLA-B*0703 and HLA-DRB1*0301 in HongKong population, however, Lin's results showed that HLA-B*4601 and HLA-B*5401 were closely related to SARS-CoV infection." (PMID 18312678, 2008). "Allele typing of 37 probable SARS patients in Taiwan identified an association between HLA-B*4601 and SARS-CoV infection; however, this was not confirmed in a study of 90 serologically confirmed SARS-CoV patients in Hong Kong." (PMID 32695122, 2020). "In the research on SARS, it was found that HLA-B*46:01 and HLA-DRB1*12:02 were related to the development of SARS, and HLA-Cw*08:01 was a susceptibility gene for SARS-CoV infection but not necessarily related to the severity of the disease." (PMID 35154095, 2022).
acute lymphoblastic leukemia (6 papers, 2016 to 2024). Leukemia with an acute onset, characterized by the presence of lymphoblasts in the bone marrow and the peripheral blood. "In a clinical study, a 9-year-old child with acute lymphoblastic leukemia (ALL) that had received allo-transplantation, with an HLA-A HLA-B, HLA-DRβ1 identical and unrelated female donor, developed grade IV aGvHD at day 70 post-transplant." (PMID 30595970, 2018). "However, most patients evaluated by Schaap and coworkers were diagnosed with acute lymphoblastic leukemia (ALL), donors were HLA-A, HLA-B, HLA-DRB1, and HLA-DQB1-identical siblings, and all patients who were evaluated received TCD grafts." (PMID 34950586, 2021). "Participants in UKALL14 had B-cell or T-cell acute lymphoblastic leukaemia, were aged 25–65 years (BCR-ABL1-negative) or 18–65 years (BCR-ABL1-positive), and for this subcohort had a fit, matched sibling donor or an 8 out of 8 allelic matched unrelated donor (HLA-A, HLA-B, HLA-C, and HLA-DR)." (PMID 35358442, 2022).
colon carcinoma (6 papers, 2003 to 2022). "RNA-seq data from The Cancer Genome Atlas (TCGA) and the Genotype-Tissue Expression project (GTEx) revealed that both PYGL and HLA-B were expressed at higher levels in normal tissues adjacent to colon cancer than in tumor tissues or normal tissues derived from subjects without cancer." (PMID 35204406, 2022). "We found that the SW480 colon carcinoma cell line had methylated the HLA-B locus." (PMID 17192185, 2006).
Alzheimer disease (5 papers, 2006 to 2024). A progressive, neurodegenerative disease characterized by loss of function and death of nerve cells in several areas of the brain leading to loss of cognitive function such as memory and language. "In our study, we identified the association between HLA-B*07:02 and T2* in hippocampus, which is affected at the early stage in Alzheimer's disease." (PMID 35441133, 2022).
cutaneous melanoma (5 papers, 2015 to 2023). A primary melanoma arising from atypical melanocytes in the skin. "As already shown by our group and others, a decreased expression of several HLA class I APM components, such as TAP1, HLA-A, HLA-B and HLA-C, has been associated with poor patient survival in several types of cancer, including cutaneous melanoma." (PMID 32825219, 2020). "As for HLA-B, numerous studies have demonstrated that the expression patterns of HLA were significantly associated with progression and metastasis in cutaneous melanoma." (PMID 33324561, 2020).
Graves disease (5 papers, 2007 to 2022). Graves' disease is an autoimmune disorder that leads to overactivity of the thyroid gland (hyperthyroidism).It is caused by an abnormal immune system response that causes the thyroid gland to produce too much thyroid hormones. "For instance, HLA-B*46:01 is associated with Graves' disease in Taiwan." (PMID 35991636, 2022).
hepatitis C (5 papers, 2010 to 2026). "Multivariate analysis showed that an HIV‐DNA level <1.5 log was significantly associated with a low HIV‐RNA level at inclusion, the presence of HLA‐B*27 and/or B*57 alleles and hepatitis C seronegativity." (PMID 30629340, 2019). "Moreover, a clear association between HLA-B*27 genotype and clearance of hepatitis C virus infection has been reported." (PMID 20531935, 2010). "We also noted that 11/37 (29.7%) carriers of HLA-B*57 had died among the HIV and HIV/HCV infected patients, while all HLA-B*57 positive patients with hepatitis C had survived." (PMID 26241854, 2015). "HLA-B*57 is a genetic host factor for spontaneous resolution of hepatitis C and delayed disease progression in HIV infection, reflecting that presence HLA-B*57 probably leads to a more efficient / active immune system." (PMID 26241854, 2015).
injury (5 papers, 2012 to 2026). Damage inflicted on the body as the direct or indirect result of an external force, with or without disruption of structural continuity. "Furthermore, allopurinol-induced liver injury (DILI) was found to be associated with HLA-A*34:02, HLA-B*53:01, and HLA-B*58:01." (PMID 36672685, 2023). "Moreover, we showed that the people with the haplotype HLA-B*51-DRB1*09 were also susceptible to HFRS, and the allele HLA-B*46 and haplotypes HLA-B*46-DRB1*09 and HLA-B*51-DRB1*09 in patients could contribute to a more severe degree of HFRS and more serious kidney injury." (PMID 23091554, 2012).
Obesity (5 papers, 2021 to 2025). Accumulation of substantial excess body fat. "Obesity (grade I or II) was more prevalent in the HLA-B*27-negative group (35.71%) than in the HLA-B*27-positive group (18.18%)." (PMID 40868248, 2025). "However, although harmless in healthy subjects, G. cambogia could determine the occurrence of hepatic adverse reactions in more susceptible people due, for instance, to the presence of HLA-B*35:01 polymorphism, or concomitant pathologies, such as obesity, or under pharmacological treatment." (PMID 37760074, 2023).
prostate carcinoma (5 papers, 2003 to 2025). A carcinoma that arises from epithelial cells of the prostate gland. "HLA-A and HLA-B 2-mismatch were risk factors of prostate cancer after KT, while HLA-DR 1-mismatch and 2-mismatch were both risk factors of prostate cancer after KT." (PMID 41001029, 2025). "2-mismatch in HLA-A and HLA-B groups was a risk factor of prostate cancer after KT [1.19(1.01~1.40)]; 2-mismatch and 1-mismatch were both risk factors of prostate cancer after KT in the HLA-DR group [1.32(1.13~1.54)], [1.20(1.03~1.39)]." (PMID 41001029, 2025). "HLA-A and HLA-B 2-mismatch are risk factors of prostate cancer after KT, while HLA-DR 1-mismatch and 2-mismatch are both risk factors of prostate cancer after KT." (PMID 41001029, 2025). "CTSS and class II MHC genes were once again the most important features, though HLA-B and HLA-C appeared more influential in prostate cancer risk." (PMID 37173324, 2023).
pulmonary hypertension (5 papers, 2015 to 2024). Increased pressure within the pulmonary circulation due to lung or heart disorder. "The HLA-B*35 allele has emerged as an important risk factor for the development of isolated pulmonary hypertension in patients with scleroderma." (PMID 37708194, 2023). "HLA-B*35 is associated with increased risk of developing pulmonary hypertension in SSc patients." (PMID 26669670, 2015).
rash (5 papers, 2009 to 2025). "CYP2C9*3 is associated with PHT-induced rash (OR: 7.05; 95% CI: 2.44–20.4; p = 0.0022).HLA-B*51:01 also showed association (OR: 3.19; 95% CI: 1.37–7.48; p = 0.010)." (PMID 40873549, 2025). "A strong association of HLA‐B*35:05 allele expression and nevirapine‐induced skin rash was established in a population of HIV‐1+ Thai patients giving evidence for HLA‐B*35:05 as a predictor for hypersensitivity to the antiviral drug nevirapine." (PMID 37811811, 2024). "Therefore, the association between OXC-induced skin rashes and other HLA alleles beyond HLA-B should be explored in future research." (PMID 23829937, 2013). "It is, thus, necessary to investigate whether or not HLA-B*3505 is also overrepresented in NVP-rash cases in our study." (PMID 19845952, 2009).
systemic lupus erythematosus (5 papers, 2019 to 2025). An autoimmune multi-organ disease typically associated with vasculopathy and autoantibody production. "The most prescribed tests were rheumatoid factor, anti-CCP antibodies, antibodies panels for lupus, myositis and scleroderma, HLA-B27, HLA-B51, HLA-B*5801, TPMT and G6PD deficiency." (PMID 34839831, 2021). "Moreover, the MICA129 met/met genotype was linked to juvenile SpA (independently of HLA-B*27 status) in Algerian patients, rheumatic disease-associated IBD in Spanish patients and systemic lupus erythematosus in Japanese patients." (PMID 30177859, 2019).
acute GVHD (4 papers, 2007 to 2022). "For instance, despite a single amino acid in an HLA Class I antigen, mismatches between HLA-B*4402 and HLA-B*4403 is associated with transplant rejection and acute graft-versus-host disease." (PMID 27047489, 2016). "We determined that acute GVHD grade II-IV occurrence was remarkably increased in the presence of HLA-B*07 and HLA-DRB1*07." (PMID 37543907, 2022). "The probability of grades III–IV acute GVHD was 61% among haplotype-mismatched patients who differed in linkage from HLA-B to HLA-A and 62% among those who differed in linkage from HLA-B to HLA-DRB1." (PMID 17378697, 2007). "HLA-B*51, HLA-B*52 and HLA-DRB1*15 had a significant decreasing impact on the incidence of grades II-IV acute GVHD." (PMID 37543907, 2022).
acute leukemia (4 papers, 2013 to 2026). A clonal (malignant) hematopoietic disorder with an acute onset, affecting the bone marrow and the peripheral blood. "In Section 2.3 of this manuscript, we described that HLA-B*35 was significantly associated with acute leukemia." (PMID 34064810, 2021). "In conclusion, we determined that, just like in other regions of the world, certain HLA-B alleles are associated with acute leukemia in Mexican population." (PMID 24364037, 2013). "Given the relatively high incidence of acute leukemia in the Mexican population, the aim of this work was to analyze gene frequencies of HLA-B alleles in Mexican patients with ALL and AML." (PMID 24364037, 2013). "An Algerian study indicated that in patients from western and southwestern Algeria, HLA-B*27 and HLA-B*58 may be correlated with an elevated risk of acute leukemia." (PMID 40508101, 2025). "Only HLA-B*35 was significantly more frequent in childhood acute leukemia than in controls (34.0% vs. 12.0%, p = 0.0005, Pc = 0.009)." (PMID 34064810, 2021).
chronic hepatitis B (4 papers, 2017 to 2025). "Participants switched to dolutegravir/abacavir/lamivudine (85%) or dolutegravir/tenofovir disoproxil fumarate/lamivudine in case of a positive HLA-B*5701 assay or chronic hepatitis B infection." (PMID 31907064, 2020). "This study aims to further screen the T-cell epitopes restricted by 15 prevalent HLA-B and 14 prevalent HLA-C allotypes and establish a universal assay for counting reactive HBV-specific T cells in patients with chronic hepatitis B (CHB)." (PMID 41583498, 2025).
cytomegalovirus infection (4 papers, 2018 to 2025). A herpesvirus infection caused by Cytomegalovirus. "At least for those HLA alleles detected by the applied HC10 antibody (all HLA-B and HLA-C alleles and several HLA-A alleles) this indicates a strong downmodulating effect of HCMV infection." (PMID 32596168, 2020). "HLA-B has been annotated to several pathways, such as natural killer cell mediated cytotoxicity, human cytomegalovirus infection, and Epstein–Barr virus infection, all of which have been implicated in MS development." (PMID 40577117, 2025).
DRESS syndrome (4 papers, 2019 to 2025). "Allopurinol is one of the most commonly implicated drugs in DRESS syndrome, and its risk is significantly higher in individuals with renal impairment or those who carry the HLA-B*58:01 allele." (PMID 41041101, 2025). "In conclusion, we present the first discovery of a polymorphism in HLA-B*15:02 in a case of DRESS syndrome induced by ceftazidime." (PMID 39188942, 2024). "Here, we present the first report of a polymorphism in HLA-B*15:02 in a case of DRESS syndrome induced by ceftazidime." (PMID 39188942, 2024). "Therefore, HLA-B*15:02 could serve as a specific risk marker for Chinese patients susceptible to ceftazidime-induced DRESS syndrome." (PMID 39188942, 2024).
Genital ulcers (4 papers, 2011 to 2023). "In addition, HLA-A*30:04 was associated with genital ulcers in HLA-B*51 non-carriers (OR = 3.89, P = 0.002, Pc = 0.048)." (PMID 21429233, 2011).
periodontitis (4 papers, 2017 to 2023). An acute or chronic inflammatory process that affects the tissues that surround and support the teeth. "Additionally, LRPPRC may potentially impact the MHC molecules HLA-B and HLA-DOA in periodontitis." (PMID 37892851, 2023). "However, this study could not demonstrate any associations of HLA‐B and HLA‐DRB types with the salivary level of aMMP‐8 among subjects with or without periodontitis." (PMID 34448550, 2021).
rheumatic disease (4 papers, 2019 to 2025). "Most patients with HLA-B*27/44 and B*44/44 genotypes had definitive rheumatic disease." (PMID 39336927, 2024). "The study aimed to investigate the clinical, paraclinical, and psychosocial differences between HLA-B*27-positive and -negative individuals diagnosed with rheumatic diseases, in order to better understand the implications of HLA-B27 status on disease expression and patient quality of life." (PMID 40868248, 2025).
Sepsis (4 papers, 2015 to 2025). Sepsis is defined as life-threatening organ dysfunction caused by a dysregulated host response to infection. "When patients were treated with HAART, however, HLA-B*57 was associated with increased mortality and risk to die from bacterial infections and sepsis, suggesting an ambiguous role of HLA-B*57 for survival in HIV/HCV infection depending on the circumstances." (PMID 26241854, 2015). "Our findings show that, in virally suppressed HIV infection, HLA-B*57 is associated with enhanced responsiveness of inflammatory innate immune cells to TLR ligands, possibly contributing to increased vulnerability in sepsis." (PMID 33278000, 2021). "Only a small number of host genes were differentially expressed between the Gram-positive (HLA-B, SERPINB10, LOC105377885, CEACAM6, NIPA2) and Gram-negative (CBFA2T3, LOC107987303, MARCO) sepsis samples in our cohort." (PMID 40965975, 2025).
Takayasu arteritis (4 papers, 2012 to 2023). A rare inflammatory large-vessel vasculitis primarily affecting the aorta and its major branches, but also other large vessels, causing stenosis, occlusion, or aneurysm. "A risk allele (rs103294) in LILRA3 is involved in the deletion of the gene, and the epistasis of LILRA3 and HLA-B*52 might play an important role in Takayasu’s arteritis (TA), possibly by over activating NK cells." (PMID 38022598, 2023).
tuberculosis (4 papers, 2007 to 2024). A chronic, recurrent infection caused by the bacterium Mycobacterium tuberculosis. "tuberculosis ORFs were searched for HLA-B*35 restricted CD8+ T-cell epitopes, common HLA-B type in West Africa142." (PMID 38461350, 2024). "Comparison of HLA-B allele frequencies distribution between patients who developed ARV and anti-tuberculosis drugs induced liver toxicity (cases) and patients who did not (treatment tolerants)." (PMID 28289388, 2017). "Researchers have studied the relationship among HLA‐B, HLA‐C and KIR genotypes, HIV‐1 infection, and immune reconstitution inflammatory syndrome (IRIS) in tuberculosis and HIV‐coinfected patients." (PMID 33657268, 2021). "Comparison of proportion of HLA-B allele carriers between patients who developed ARV and anti-tuberculosis drugs induced liver injury (cases) and patients who did not (treatment tolerants)." (PMID 28289388, 2017).
uveal melanoma (4 papers, 2016 to 2024). A melanoma derived from melanocytes of the uveal tract. "Only the GNA11Q209L FRMVDVGGL epitope, restricted to HLA-B*27:05 and B*39:01, is the most frequent mutation in uveal melanoma (42,50% of all cases reported in TCGA)." (PMID 38600547, 2024). "Furthermore, in uveal melanoma, which is a rare malignancy in which NK cells are believed to be key mediators in preventing metastasis formation, HLA-B*44 allele carriers were reported to have a significantly inferior survival." (PMID 37597015, 2023). "Loss of heterozygosity on chromosome 6p has also been reported in primary uveal melanoma without a correlate with HLA-A and HLA-B monomorphic expression." (PMID 33317028, 2020).
ZIKV infection (4 papers, 2018 to 2025). "Results show that HLA-B*0702 mice immunized with the ZIKV-NS poly-epitope, which contains five epitopes from ZIKV, of which only two have sequences shared with DENV2, are protected against ZIKV infection, but not against DENV2 infection." (PMID 39418312, 2024).
anterior uveitis (3 papers, 2023 to 2024). Inflammation of the iris and anterior chamber of the eye. "We also stratified the clinical manifestations for the most common subtypes (HLA-B*51:01 and HLA-B*51:08) and found that anterior uveitis was less common in the case of B*51:01 positivity than in the case of B*51:08 positivity (24.1 and 46.1%, respectively; P < 0.05; OR 0.37; CI 0.17–0.80)." (PMID 37937176, 2023).
attention deficit-hyperactivity disorder (3 papers, 2014 to 2021). A disorder characterized by a marked pattern of inattention and/or hyperactivity-impulsivity that is inconsistent with developmental level and clearly interferes with functioning in at least two settings (e.g. at home and at school). "Specifically, the A2 allele of HLA-A, several HLA-B alleles, as well as HLA-DRB1 DR4 have been reported to be associated with ASD, the latter also being associated with attention deficit hyperactivity disorder (ADHD)." (PMID 30976114, 2019).